MIR942 (microRNA 942)
Synonyms: hsa-mir-942; MIRN942; mir-942
Gene: MicroRNA gene on chromosome 1 (117,094,643 to 117,094,728, forward strand). Ensembl gene ENSG00000215930.
Gene Ontology:
Biological process: miRNA-mediated post-transcriptional gene silencing
Cellular component: RISC complex
Homologues: Orthologues: chimpanzee ptr-mir-942 (100% identical), macaque mml-mir-942 (95% identical).